STIM1 (stromal interaction molecule 1)
Description:
Acts as a Ca(2+) sensor that gates two major inward rectifying Ca(2+) channels at the plasma membrane: Ca(2+) release-activated Ca(2+) (CRAC) channels and arachidonate-regulated Ca(2+)- selective (ARC) channels. Plays a role in mediating store-operated Ca(2+) entry (SOCE), a Ca(2+) influx following depletion of intracellular Ca(2+) stores. Upon Ca(2+) depletion, translocates from the endoplasmic reticulum to the plasma membrane where it activates CRAC channel pore-forming subunits ORA1, ORA2 and ORAI3 to generate sustained and oscillatory Ca(2+) entry. Involved in enamel formation. Plays a role in regulating the type I interferon response by retaining the signaling adapter STING at the endoplasmic reticulum.
Synonyms: GOK; D11S4896E; IMD10; STRMK; TAM; TAM1
Tractability: Small molecule: a high-quality ligand is known. Antibody: its Gene Ontology location is reachable by antibodies, with high confidence; UniProt places it where antibodies can reach, with medium confidence; UniProt predicts a signal peptide or a membrane-spanning region. PROTAC: ubiquitination databases record sites on it; its protein half-life has been measured; a small molecule that binds it is known.
Gene: Protein-coding gene on chromosome 11 (3,854,527 to 4,093,210, forward strand). Ensembl gene ENSG00000167323.
Subcellular location: Cell membrane; Endoplasmic reticulum membrane; Cytoplasm, cytoskeleton; Sarcoplasmic reticulum
Subcellular location (Human Protein Atlas): Endoplasmic reticulum
Pathways (Reactome):
Hemostasis: Elevation of cytosolic Ca2+ levels
Immune System: Antigen activates B Cell Receptor (BCR) leading to generation of second messengers
Muscle contraction: Ion homeostasis
Gene Ontology:
Molecular function: calcium channel regulator activity; calcium ion binding; identical protein binding; microtubule plus-end binding; protease binding; protein binding
Biological process: activation of store-operated calcium channel activity; detection of calcium ion; enamel mineralization; positive regulation of adenylate cyclase activity; positive regulation of angiogenesis; regulation of calcium ion transport; regulation of store-operated calcium entry; store-operated calcium entry; intracellular calcium ion homeostasis
Cellular component: cortical endoplasmic reticulum; endoplasmic reticulum; endoplasmic reticulum membrane; plasma membrane; plasma membrane raft; sarcoplasmic reticulum; sarcoplasmic reticulum membrane; cytoskeleton
Genetic constraint (gnomAD): Loss-of-function variants: 25 observed, 73.44 expected, observed/expected ratio (o/e) 0.34, 90% interval 0.25 to 0.47. The upper end of that interval is the gene's LOEUF score, 0.47, which puts it in group 2 of 6, group 1 being the genes least tolerant of losing a copy. Missense variants: 722 observed, 938.15 expected, observed/expected ratio (o/e) 0.77, 90% interval 0.72 to 0.82. Synonymous variants: 324 observed, 357.08 expected, observed/expected ratio (o/e) 0.91, 90% interval 0.83 to 1.
Gene-disease validity (ClinGen):
ClinGen rates the evidence that STIM1 causes each of these diseases.
combined immunodeficiency due to STIM1 deficiency (autosomal recessive): Definitive. Aform of combined immunodeficiency due to Calcium release activated Ca2+(CRAC) channel dysfunction characterized by recurrent infections, autoimmunity, congenital myopathy and ectodermal dysplasia.
tubular aggregate myopathy (autosomal dominant): Definitive. Tubular aggregate myopathy is a disorder that affects the skeletal muscles.
Homologues: Orthologues: guinea pig STIM1 (97% identical), dog STIM1 (97% identical), chimpanzee STIM1 (96% identical), macaque STIM1 (95% identical), rat Stim1 (93% identical), mouse Stim1 (92% identical), pig STIM1 (91% identical), rabbit STIM1 (89% identical), tropical clawed frog stim1 (70% identical), zebrafish stim1a (61% identical), zebrafish stim1b (54% identical), Drosophila melanogaster Stim (28% identical), and 1 more. Paralogues in human: STIM2 (46% identical).
Diseases named in the same sentence as STIM1 in open-access papers:
STIM1 is named in the same sentence as 271 diseases in open-access papers, as found by Europe PMC text mining. Sharing a sentence is not in itself a finding about the gene and the disease. The quoted sentences say what the papers report.
breast carcinoma (78 papers, 2012 to 2025). "Single nucleotide variants in STIM1 are associated with an increased risk of tumor progression in patients with HER2-positive breast cancer." (PMID 40491474, 2025). "The aim of this study was to analyze Orai1 and STIM1 N-linked glycosylation in SOCE in breast cancer cells and to ascertain the potential functional relevance of this post-translational modification in the development of cancer hallmarks." (PMID 36612199, 2022). "While our study illustrates the associations between STIM1 genetic variants and clinical stage, we also found that patients with the risk alleles of rs2304891 or rs3750996 have a higher risk of late-stage breast cancer especially in ER+ or PR+ tumors." (PMID 33348924, 2020). "The development of diverse cancer types such as glioblastoma, breast cancer, prostate cancer, and hepatocellular carcinoma has been linked to an upregulated expression of STIM1 proteins." (PMID 33333945, 2020). "Four tagging germline single nucleotide variants (SNVs) in STIM1 were selected and RNA sequencing data of 525 breast cancer samples from The Cancer Genome Atlas (TCGA) database were evaluated." (PMID 33348924, 2020). "Breast cancer metastasis has been linked to STIM1/Orai1-mediated Ca2+ influx and several studies also highlighted the upregulation of STIM1 and Orai1 in basal breast cancers." (PMID 32764353, 2020). "In light of the fact that STIM1 has been reported to link to cellular migration of cancer cells, our results further indicate a clinical role of STIM1 variants in the risk of breast cancer." (PMID 33348924, 2020). "An increase in STIM1/STIM2 gene expression ratio has been associated with reduced survival in breast cancer patients." (PMID 23594099, 2013). "This study showed that the level of STIM1 expression is directly associated with metastasis and reduced survival among breast cancer patients, and blocking store-operated calcium entry reduces the migration of breast cancer cells." (PMID 34573310, 2021). "Genetic variants of STIM1 associated with the development of breast cancer might be connected through the alteration of STIM1 expression." (PMID 33348924, 2020). "Thus, the aim of the current study was to investigate the correlation between genetic variants of STIM1 and clinical outcomes of breast cancer." (PMID 33348924, 2020). "Our observation of poorer RFS in some breast cancer subtypes with high ORAI3 and low ORAI1 levels, is reflective of the association between the ORAI1 activators STIM1/STIM2 in basal breast cancers, where high STIM1/low STIM2 was associated with poorer survival." (PMID 30754719, 2019). "Furthermore, both STIM1 and Orai1 were implicated in cell migration in breast cancer cells and cervical cancer cells." (PMID 22984609, 2012). "The authors found that breast cancer tissues overexpress STIM1 compared to the surrounding normal tissue and showed an inverse correlation between STIM1 and miR-223 expression in these tissues." (PMID 39125761, 2024). "Stromal Interaction Molecule 1 (STIM1) promotes angiogenesis by reducing exosomal miR-145 in breast cancer MDA-MB-231 cells." (PMID 38794316, 2024). "STIM1 is not only highly expressed in breast cancer, but also displays increased expression in 89% of head and neck squamous cell carcinoma (HNSCC)." (PMID 37932320, 2023). "By contrast, breast cancer cells scape from this regulatory mechanism, so that, SOCE is independent on STIM1 or Orai1 N-linked glycosylation." (PMID 36612199, 2022). "Next, we have explored the possible role of STIM1 N-linked glycosylation in TG-induced apoptosis in MCF10A cells and the breast cancer cell lines MCF7 and MDA-MB-231." (PMID 36612199, 2022). "In MDA-MB-231 breast cancer cells, stromal interaction molecule 1 (STIM1) downregulates exosomal miRNA-145 to promote angiogenesis." (PMID 36096820, 2022). "In breast cancer cells, inhibitors of α-glucosidases have been reported to attenuate STIM1 expression, which significantly reduces SOCE and cell migration." (PMID 36612199, 2022).
breast carcinoma (continued). "It is worth to mention that both CHX and tunicamycin have a smaller effect in MDA-MB-231 cells than in MCF10A cells, thus suggesting that Orai1 and STIM1 protein degradation is slower in MDA-MB-231 breast cancer cells." (PMID 36612199, 2022). "SPCA2 has been reported to induce the constitutive activity of Orai1 independently of STIM1 in breast cancer cells." (PMID 34944977, 2021). "Taken together, our findings suggest that STIM1 promotes angiogenesis by reducing exosomal miR-145 in breast cancer MDA-MB-231 cells." (PMID 33414420, 2021). "Understandably, therefore, a high STIM1/STIM2 ratio in breast cancer cells combined with increased SOCE correlates with poorer prognosis in patients." (PMID 34572262, 2021). "Consistently, in MDA-MB-231 breast cancer cells knockdown of either STIM1 or Orai1 slows down cell migration, which is due to impairment in the focal adhesion turnover." (PMID 34069353, 2021). "One of the pioneer studies demonstrating the proinvasive role of STIM1/ORAI1 in breast cancer cells determined that SOCE enhanced turnover of Rac- and Ras-based focal adhesions to increase cancer cell migration." (PMID 34572262, 2021). "This was first assessed in the context of breast cancer where STIM1 and Orai1 were shown to be important for breast cancer cell migration and metastasis to the lung using xenograft mouse models." (PMID 34069353, 2021). "Recently, we investigated the effect of exosomes from STIM1-knockout breast cancer MDA-MB-231 cells (Exo-STIM1-KO), and from SKF96365-treated MDA-MB-231 cells (Exo-SKF) on angiogenesis in human umbilical vein endothelial cells (HUVECs) and nude mice." (PMID 33414420, 2021). "A combination of knockdown and rescue strategies in the breast cancer cell line MDA-MB231 has revealed that STIM1 and Orai1 play a major role in breast cancer cell migration." (PMID 33333945, 2020). "Expression of STIM1 and Orai proteins have been verified for instance in breast cancer, lung cancer, glioma carcinoma, colorectal cancer, cervical cancer, prostate cancer, hepatocellular carcinoma, gastric cancer, and others." (PMID 33333945, 2020). "We further identified the correlation between STIM1 gene expression and clinical outcomes of breast cancer by using the TCGA database." (PMID 33348924, 2020). "Gene chip microarray of 295 breast cancer patients revealed a high STIM1 and low STIM2 expression in basal-like tumours that have a particularly poor prognosis and few treatment options." (PMID 32825277, 2020). "SOCE was first linked to tumour cell migration and metastasis in MDA-MB-231 breast cancer cells, where siRNA-induced silencing of Orai1 or STIM1, or treatment with the SOCE blocker SKF96365, reduced in vitro migration and invasion." (PMID 32825277, 2020). "In conclusion, our results suggest that germline SNV, rs2304891 and rs3750996 as well as STIM1 expression are important biomarkers for the prediction of clinical outcomes in breast cancer patients." (PMID 33348924, 2020). "Our findings show that STIM1 expression is differentially regulated by the miRNA machinery in different cell types and argue for a role for this regulation in breast cancer." (PMID 31506588, 2019). "Similar results were found in breast cancer cells in a murine tumor metastasis model, in colorectal cancer following a destabilization of STIM1, and in glioma cell lines." (PMID 30935064, 2019). "The defects in focal adhesion turnover and cell migration in breast cancer cells with STIM1/Orai1 silencing or SOCE blockade were rescued by the small GTPases Ras and Rac." (PMID 31252656, 2019). "Our results show that STIM1 miRNA-dependent post-transcriptional regulation is used effectively to regulate STIM1 expression in two different breast cancer cell lines." (PMID 31506588, 2019).
breast carcinoma (continued). "The results from MCF7 and MDA-MB-231 cells argues for Ago2 downregulation as a mechanism to lower the effectiveness of the miRNA machinery in aggressive breast cancer cells resulting in increased STIM1 expression to support cell migration." (PMID 31506588, 2019). "The role of STIM1 and Orai1 in cancer migration and metastasis initially came from studies in breast cancer and cervical cancer." (PMID 31252656, 2019). "Overexpression of STIM1 and Orai1 is shown in many cancer types like prostate cancer, breast cancer, glioblastoma and hepatocellular carcinoma." (PMID 31366337, 2019). "Consistently, STIM1 expression correlates with a poorer prognosis in aggressive basal-like breast cancers." (PMID 31506588, 2019). "Recent studies on melanoma, breast cancer cells and v-Src-transformed mouse embryonic fibroblasts (MEFs) uncover STIM1 dependent SOCE as the principle Ca2+ signals that control invadopodia formation." (PMID 31252656, 2019). "The molecular mechanisms by which STIM1/Orai1-dependent SOCE regulates tumor cell migration were highlighted in studies on breast cancer and cervical cancer." (PMID 31252656, 2019). "We also examined the expression of STIM2 and STIM1 in a panel of breast cancer cell lines and found a higher level of STIM2 in two mesenchymal-like cell lines (MDA-MB-231, BT-549) than in three epithelial-like cell lines (T-47D, BT-474, and MCF7)." (PMID 31464639, 2019). "STIM1 was also shown to play a role in exogenous transforming growth factor (TGF)-β-induced EMT in breast cancer cells." (PMID 31464639, 2019). "In breast cancer, STIM1 and STIM2 contribute to invasion, migration, and SOC-dependent TGFβ-mediated EMT (epithelial-mesenchymal transition), and their overexpression significantly correlates with the poor survival." (PMID 31226817, 2019). "Consistent with this, transforming growth factor (TGF)-β induces cell cycle arrest at the G0/G1 phase and impair cell proliferation in MDA-MB-231 and MCF7 breast cancer cells by a mechanism that involves decreased STIM1 expression and, subsequently, SOCE." (PMID 30558192, 2018). "The basal subtype breast cancers are also more likely to have higher mRNA levels of the canonical ORAI channel activator STIM1, and lower levels of its related isoform STIM2." (PMID 30034631, 2018). "The expression level of STIM1 differs among the members of different breast cancer cell line subtypes." (PMID 30558192, 2018). "In contrast, in the non-tumoral MCF10A cell line, treatment with CO-OCS was unable to alter the expression of STIM1 or Orai1, which indicates that protein glycosylation plays a relevant role in STIM1 expression and breast cancer cell migration." (PMID 30558192, 2018). "The role of SOCE regulated by STIM1 has been shown to control the actomyosin contractility during breast cancer cell migration." (PMID 28495532, 2018). "For instance, pharmacological inhibition of SOCE with SKF or silencing of ORAI1 and STIM1 was shown to inhibit cell migration in MDA-MB-231 breast cancer cells." (PMID 30034631, 2018). "Knockdown of Stim1 or pharmacological inhibition of SOCE suppressed tumor metastasis in animal models of breast cancer." (PMID 28326487, 2017). "Stim1 is the origin of SOCE, which has been implicated in several pathological processes of cancer, such as liver and breast cancer cell migration and metastasis." (PMID 28326487, 2017). "The survival of breast cancer patients with high STIM1 mRNA levels in tumors was significantly reduced compared with the control group." (PMID 27013185, 2016). "In contrast to epithelial breast cancer cells, STIM1 is involved in the formation of this complex in lipid-rafts where SK3 was localized." (PMID 27102434, 2016). "STIM1 played an important role in gene regulation by controlling the ER calcium homeostasis in breast cancer cells." (PMID 27199756, 2016). "Knockdown or pharmacological inhibition of STIM1–Orai1 can thus effectively confine the growth and metastasis of breast cancer." (PMID 27199756, 2016).